SNORD5 (small nucleolar RNA, C/D box 5)
Synonyms: mgh28S-2410
Gene: Small nucleolar RNA gene on chromosome 11 (93,733,228 to 93,733,300, reverse strand). Ensembl gene ENSG00000239195.
Gene Ontology:
Biological process: RNA processing
Cellular component: nucleolus
Homologues: Orthologues: macaque SNORD5 (97% identical), rat Snord5 (90% identical), mouse Gm24299 (85% identical).